RN7SL33P (RNA, 7SL, cytoplasmic 33, pseudogene)
Gene: Miscellaneous RNA gene on chromosome 17 (2,557,753 to 2,558,094, reverse strand). Ensembl gene ENSG00000243049.
Homologues: Orthologues: chimpanzee Metazoa_SRP (99% identical). Paralogues in human: RN7SL775P (77% identical), RN7SL526P (75% identical), RN7SL317P (74% identical), RN7SL487P (73% identical), Metazoa_SRP (72% identical), RN7SL40P (72% identical), Metazoa_SRP (71% identical), RN7SL2 (71% identical), RN7SL1 (70% identical), Metazoa_SRP (70% identical), RN7SL740P (70% identical), RN7SL3 (69% identical), and 701 more.